STARD5 (StAR related lipid transfer domain containing 5)
Description:
May be involved in the intracellular transport of sterols or other lipids. May bind cholesterol or other sterols (By similarity).
Synonyms: MGC10327
Tractability: No criterion of Open Targets' tractability assessment is met for any kind of drug.
Gene: Protein-coding gene on chromosome 15 (81,309,053 to 81,324,183, reverse strand). Ensembl gene ENSG00000172345.
Subcellular location (Human Protein Atlas): Vesicles; Cytosol
Pathways (Reactome):
Metabolism: Recycling of bile acids and salts
Gene Ontology:
Molecular function: bile acid binding; cholesterol binding; cholesterol transfer activity; lipid binding
Biological process: cholesterol import; bile acid and bile salt transport
Cellular component: cytosol
Genetic constraint (gnomAD): Loss-of-function variants: 28 observed, 27.04 expected, observed/expected ratio (o/e) 1.04, 90% interval 0.77 to 1.42. The upper end of that interval is the gene's LOEUF score, 1.42, which puts it in group 5 of 6, group 1 being the genes least tolerant of losing a copy. Missense variants: 254 observed, 265.78 expected, observed/expected ratio (o/e) 0.96, 90% interval 0.86 to 1.06. Synonymous variants: 101 observed, 97.3 expected, observed/expected ratio (o/e) 1.04, 90% interval 0.88 to 1.23.
Homologues: Orthologues: chimpanzee STARD5 (99% identical), pig STARD5 (86% identical), guinea pig STARD5 (84% identical), mouse Stard5 (84% identical), dog STARD5 (82% identical), macaque STARD5 (82% identical), rabbit STARD5 (80% identical), rat Stard5 (75% identical), tropical clawed frog stard5 (62% identical), zebrafish stard5 (50% identical), Caenorhabditis elegans tag-340 (25% identical), Caenorhabditis elegans K02D3.2 (25% identical), and 1 more. Paralogues in human: STARD4 (32% identical), STARD6 (30% identical), STARD3 (26% identical), STAR (23% identical), STARD3NL (8% identical).
Diseases named in the same sentence as STARD5 in open-access papers:
STARD5 is named in the same sentence as 18 diseases in open-access papers, as found by Europe PMC text mining. Sharing a sentence is not in itself a finding about the gene and the disease. The quoted sentences say what the papers report.
Hepatic steatosis (3 papers, 2023 to 2025). Steatosis is a term used to denote lipid accumulation within hepatocytes. "The hepatic steatosis was clearly present in all mice, as evidenced by the vacuolization of cells in liver samples of WT and StarD5−/− mice." (PMID 40362395, 2025). "Conversely, lingering downregulation of StarD5 with prolonged lipid-cholesterol excess accelerates fatty liver’s transition to fibrosis; mediated via dysregulation in the oxysterol signaling pathway." (PMID 38591148, 2024). "In addition, NAS scores were determined in the liver sections to assess MASH; while NAS scores for WT mice were 1–2, grades for StarD5−/− mice liver slides were 4–5, indicating a more severe hepatic steatosis compared with WT mice." (PMID 38591148, 2024). "In hepatocytes, Stard5 reduces lipid accumulation, suggesting that Stard5 dysregulation may play an important role in fatty liver disease." (PMID 37978523, 2023). "Therefore, being able to maintain normal expression levels of StarD5 may represent a key element in the prevention of fatty liver disease." (PMID 38591148, 2024).
gastric cancer (2 papers, 2021 to 2024). A primary or metastatic malignant neoplasm involving the stomach. "Consistent with the preceding analytical results, the expression of APOA1, BCHE, and STARD5 in human gastric cancer cells (AGC, HGC-27) was significantly lower (p<0.0001) compared to normal gastric epithelial cells (GSE-1)." (PMID 38357546, 2024). "Collectively, NME2 was critical for the maintenance of stemness of gastric cancer stem-like cells via promoting the expression of stemness-associated transcriptional factors (c-Myc, LGR5, ALDH1, and Nanog) and anti-apoptosis genes (RIPK1, STARD5, and LIMS1)." (PMID 34628473, 2021). "The results of western blot and quantitative real-time PCR showed that the NME2 knockdown significantly downregulated the expression levels of RIPK1, STARD5, and LIMS1 in gastric cancer stem-like cells from human solid tumors." (PMID 34628473, 2021).
liver fibrosis (2 papers, 2024 to 2025). "WD-fed StarD5−/− mice upregulated WW domain containing transcription regulator 1 (TAZ or WWTR1) expression with accelerated liver fibrosis when compared with WD-fed WT mice." (PMID 38591148, 2024). "StarD5’s downregulation in response to abundant lipid supply led to physiologic-designed triglyceride storage, but with more chronic overabundance, as with Western diet (WD) feeding, led to the accumulation of toxic cholesterol metabolites and the acceleration of liver fibrosis." (PMID 38591148, 2024). "Thus, maintaining the expression levels of StarD5 may represent a possible therapeutic target for NASH and MAFLD, given its role in lipid homeostasis and fibrosis; its downregulation or ablation has been shown to accelerate the progression of steatosis and liver fibrosis." (PMID 40362395, 2025).
Obesity (2 papers, 2011 to 2024). Accumulation of substantial excess body fat. "As for the genes involved in lipid metabolism, Pla2g2d, Lipo3, and Naaa were significantly upregulated, promoting anabolism, while lipid-transport-related genes, such as Abcg5, Apo3, and Stard5, were down-regulated, leading to lipid surplus and diverse metabolic syndromes, such as obesity." (PMID 39007149, 2024).
steatosis (2 papers, 2024 to 2025). Increased lipid within the cytoplasm of cells. "We recently demonstrated that VLDL secretion is reduced in the absence of StarD5, likely contributing to the increased liver triglyceride content in StarD5−/− mice, making StarD5−/− mice more prone to developing steatosis and fibrosis." (PMID 40362395, 2025). "Reduced ApoB levels in the livers of StarD5−/− mice, coupled with increased triglyceride synthesis, appear to be able to drive steatosis in StarD5−/− mouse livers." (PMID 38591148, 2024). "Induction of ER stress led to increased expression of StarD5 and steatosis in the livers of wild-type (WT) mice, while in StarD5−/− mice, steatosis and apoptosis were more acute compared to WT mice, as evidenced by increased lipid accumulation and cleavage of PARP, respectively." (PMID 40362395, 2025). "Interestingly, when comparing triglyceride levels in the livers of WT and StarD5−/− mice, steatosis in StarD5−/− mice was clearly more prominent." (PMID 40362395, 2025).
asthma (1 paper, 2014). "We also found significantly lower levels of IL16 in whole lung samples from COPD patients compared with controls, in contrast to its increased expression in asthma, and significantly higher levels of STARD5 in COPD patients compared with controls." (PMID 24983941, 2014).
clear cell renal cell carcinoma (1 paper, 2023). "Currently few studies are available on Stard5 in cancer, with one paper showing that hypermethylation of the STARD5 in clear cell renal cell carcinoma is significantly associated with poor prognosis." (PMID 37978523, 2023).
fibrosis (1 paper, 2024). the formation of excess fibrous connective tissue in an organ or tissue in a reparative or reactive process. "To further define the relevance of the lack of StarD5 in the development of fibrosis, we performed a fibrosis-relative gene expression panel using liver samples from StarD5−/− and WT mice on ND and 18 wk of WD." (PMID 38591148, 2024).
hepatocellular carcinoma (1 paper, 2024). A malignant tumor that arises from hepatocytes. "It has been established that STARD5 is a valuable biomarker for assessing hepatocellular carcinoma (HCC) prognosis, and high expression of STARD5 implies a better prognosis." (PMID 38357546, 2024).
Insulin resistance (1 paper, 2024). Increased resistance towards insulin, that is, diminished effectiveness of insulin in reducing blood glucose levels. "NEW & NOTEWORTHY We have found that deletion of the cholesterol transport protein StarD5 in mice leads to an increase in insulin resistance and lipid accumulation due to the upregulation of lipid synthesis and decrease VLDL secretion from the liver." (PMID 38591148, 2024). "The development of early insulin resistance did not alter other blood parameters of StarD5−/−, which were similar to those of WT mice fed a ND or WD." (PMID 38591148, 2024).
tumor (4 papers, 2017 to 2025). "Next, patients were divided into low (negative and weakly positive) and high (moderately and strongly positive) expression groups based on Stard5 expression in the tumor tissue." (PMID 37978523, 2023). "For the first time, we show that Stard5 can act as a tumor suppressor to inhibit EMT as well as tumor progression." (PMID 37978523, 2023). "Together, these data suggest that reduced Stard5 expression in tumor tissues may be an important indicator of poor prognosis in HCC." (PMID 37978523, 2023). "Notably, we demonstrated for the first time that Stard5 acted as a tumor suppressor by inhibiting metastasis in HCC." (PMID 37978523, 2023). "Bioinformatics analysis revealed that APOA1, BCHE, and STARD5 were significantly expressed in normal samples, while CYP19A1 and PLA1A were considerably expressed in tumor samples in the TCGA-STAD cohort." (PMID 38357546, 2024).
cancer (3 papers, 2011 to 2023). A tumor composed of atypical neoplastic, often pleomorphic cells that invade other tissues. "Then we analyzed the relationship between STARDs and clinicopathological parameters in LUAD, and found that the mRNA expressions of STARD5/12/14 were positively or negatively correlated with cancer stage and lymph node stage of LUAD patients." (PMID 37790851, 2023). "Stard5 became the focus of our attention, which had hardly been studied in cancers." (PMID 37978523, 2023).
bacterial infections (1 paper, 2021). "These genes encode sensors and transcription factors that mediate induction of proinflammatory responses and apoptosis during viral and bacterial infections or regulate plasma membrane cholesterol and intracellular cholesterol homeostasis, such as StAR-related lipid transfer protein 5 (StARD5)." (PMID 34710198, 2021).
STARD5 also shares sentences with these, for which no sentence is quoted: colon cancer (1 paper); liver cancer (1); lung carcinoma (1); metabolic disorders (1); metabolic syndrome (1).